TXNIP (thioredoxin interacting protein)
Diseases named in the same sentence as TXNIP in open-access papers (continued):
Sharing a sentence is not in itself a finding about the gene and the disease.
acute myeloid leukemia (8 papers, 2014 to 2025). Acute myeloid leukemia (AML) is a group of neoplasms arising from precursor cells committed to the myeloid cell-line differentiation. "It is noteworthy that TXNIP overexpression significantly suppressed the proliferation of two acute myeloid leukemia cell lines, i.e., MOLM-13 and MV4-11." (PMID 34067290, 2021). "Although TXNIP is epigenetically silenced in acute myeloid leukemia (AML) cells, as in many cancer cells, its role in leukemogenesis remains elusive." (PMID 32511893, 2020). "Deregulation of WWP1 expression in acute myeloid leukemia (AML) blasts might accelerate TXNIP proteasomal degradation, thus increasing the ability of thioredoxin to buffer ROS, and ultimately favoring leukemic cell survival." (PMID 39364720, 2025). "Thioredoxin interacting protein (TXNIP) has been well known as a tumor suppressor in various cancers, including acute myeloid leukemia (AML)." (PMID 32511893, 2020).
dyslipidemia (8 papers, 2017 to 2025). "An association between dyslipidemia, LDL oxidation, CD36 expression, ROS generation, thioredoxin-interacting protein (TXNIP) upregulation, and NLRP3 inflammasome activation was demonstrated by DSS exposure in HFD-fed rats." (PMID 33917884, 2021). "An association between dyslipidemia, the oxidation of LDL, CD36, ROS generation, TXNIP upregulation, NLRP3 inflammasome activation, and dysbiosis has been demonstrated in the present study through the action of DSS in HFD-fed rats." (PMID 33917884, 2021). "In the present study, verapamil, identified as an inhibitor of TXNIP, improved dyslipidemia-induced neuropathy, which provides a clue to clarify this potential mechanism." (PMID 30733849, 2019). "Our finding suggests that TXNIP might be a potential target for the treatment of neuropathy in prediabetic patients with dyslipidemia." (PMID 30733849, 2019). "Therefore, it is reasonable to consider the contribution of other metabolic pathways including dyslipidemia or altered insulin sensitivity that might be affected by TXNIP deletion." (PMID 32492941, 2020). "However, whether TXNIP overexpression is involved in the onset and progression of DN remains unknown, especially diabetic patients with dyslipidemia." (PMID 30733849, 2019). "Thus, we hypothesized that TXNIP overexpression involved in the development and progression of DN in the subject with dyslipidemia." (PMID 30733849, 2019).
glioblastoma (8 papers, 2016 to 2024). The most malignant astrocytic tumor (WHO grade IV). "TXNIP, which was induced by pterostilbene, encodes a postulated tumor suppressor gene which plays an important role in oxidative homeostasis and glioblastoma cell viability." (PMID 27689322, 2016). "Our data showed that the numbers of neoantigen in tumors like CESC, KIRP, and glioblastoma multiforme (GBM) was significantly positively associated with the expression of TXNIP (all P < 0.05)." (PMID 35843949, 2022). "TXNIP acts as a tumor suppressor in glioblastoma by lowering STAT3 levels, which are increased by STAT3 inhibitors such as SS-4." (PMID 36366411, 2022). "TXNIP expression increased in glioblastoma cells in response to SS-4 treatment, indicating that STAT3 tyrosine phosphorylation decreased TXNIP expression." (PMID 36366411, 2022). "TXNIP has been found to be involved in the autophagy and ferroptosis of a class of protein disulfide isomerase inhibitors in the treatment of glioblastoma." (PMID 34869576, 2021). "RNA-Seq with the T98G glioblastoma cell line treated with GH showed more than an 80-fold reduction in thioredoxin interacting protein (TXNIP) expression, indicating that GH has a direct effect on regulating a key gene involved in the homeostasis of cellular glucose." (PMID 37175448, 2023).
Hypoglycemia (8 papers, 2013 to 2024). A decreased concentration of glucose in the blood. "With a genetic targeting strategy, we previously reported that TXNIP-WKO causes predisposition to death with hypoglycemia, hyperinsulinemia, ketosis, and abnormal liver steatosis during fasting." (PMID 32824669, 2020). "TXNIP deficient mice display severe hypoglycemia and liver steatosis." (PMID 38529321, 2024). "Since severe hypoglycemia could affect lipid metabolism and also cause death, we used male TXNIP-KO mice for the rest of this study." (PMID 35314758, 2022). "Similarly, liver specific TXNIP deletion (TXNIP-LKO) caused hypoglycemia and ketoacidosis, which is consistent with the finding of poor glucose production and increased β-hydroxybutyrate release from isolated hepatocytes from TXNIP-LKO mice." (PMID 32824669, 2020). "Moreover, TXNIP deficient mice show hyperinsulinemia with marked hypoglycemia during starvation, further linking TXNIP to β-cell function." (PMID 23691179, 2013). "Although TXNIP functions as an adaptor for the basal GLUT4 endocytosis in order to prevent hypoglycemia under fasting conditions, insulin releases TXNIP from GLUT4 and prevents GLUT4 from being endocytosed in the postprandial state." (PMID 32476292, 2020). "TXNIP-WKO exhibited abnormal liver steatosis and impaired gluconeogenesis during fasting, which may contribute the phenotype of hypoglycemia-induced predisposition for death." (PMID 32824669, 2020). "Under fasting conditions, TXNIP suppresses glucose uptake directly by binding to the glucose transporters GLUT1 and GLUT4 and by inducing GLUTs endocytosis, in order to prevent hypoglycemia." (PMID 32476292, 2020). "In the present study, we aimed to determine the role of TXNIP in fasting-induced LS by using male TXNIP-KO mice that developed LS without severe hypoglycemia." (PMID 35314758, 2022). "Thus, in insulin‐sensitive tissues (i.e., skeletal muscle and adipose tissue), TXNIP seems to decrease the number of GLUT4 transporters on the cell surface and reduce the glucose uptake in order to prevent hypoglycemia under fasting conditions." (PMID 32476292, 2020).
osteoarthritis (8 papers, 2021 to 2024). A noninflammatory degenerative joint disease occurring chiefly in older persons, characterized by degeneration of the articular cartilage, hypertrophy of bone at the margins and changes in the synovial membrane. "It was also discovered that under conditions of chronic inflammation, at least in diseases such as IVDD and osteoarthritis, the expression of TXNIP decreases." (PMID 38711073, 2024). "Here, we discuss the roles of TXNIP in the regulatory mechanisms of transcription and protein levels and summarize its involvement in bone metabolic disorders such as osteoporosis, osteoarthritis, and rheumatoid arthritis." (PMID 36059548, 2022). "In the field of osteoarthritis, TXNIP/NLRP3 signaling pathway is closely related to chondrocytes and synoviocytes, but further investigation is needed." (PMID 34539417, 2021). "Several studies have shown that targeted inhibition of the TXNIP/NLRP3 signaling pathway may also improve the pathological manifestations of osteoarthritis and promote the repair of cartilage damage in OA cell models and mouse models." (PMID 37702097, 2023). "TXNIP was also reported to activate NLRP3 inflammasomes in inflammation-related diseases, such as osteoarthritis." (PMID 38671856, 2024). "Our data are in line with other research that identified CHR-mediated inhibition of pro-fibrotic pathways in rat myocardial injury, renal fibrosis and osteoarthritis, by reducing TGF-β1/Smad3, p38, Erk1/2, MMP2 and PERK/TXNIP/NLRP3 signalling." (PMID 38169923, 2023). "Furthermore, TXNIP expression levels were notably higher in the articular chondrocytes of DMM rats compared to the SHAM group, suggesting a link between TXNIP upregulation and the progression of osteoarthritis (OA)." (PMID 39330495, 2024).
subarachnoid hemorrhage (8 papers, 2017 to 2024). A serious neurological disorder characterized by intracranial hemorrhage into the subarachnoid space. "Two other studies that employed the animal model of subarachnoid hemorrhage showed that increased TXNIP expression correlated with enhanced tissue damage, while blocking TXNIP expression with resveratrol or specific siRNAs reduced tissue damage." (PMID 39483368, 2022).
acute kidney injury (7 papers, 2016 to 2024). Sudden and sustained deterioration of the kidney function characterized by decreased glomerular filtration rate, increased serum creatinine or oliguria. "Animal studies have shown that inhibiting either TXNIP or NLRP3 can prevent acute kidney injury caused by rhabdomyolysis-induced ischemia-reperfusion injury." (PMID 39045044, 2024). "Thioredoxin-interacting protein (TXNIP) downstream of the IRE1α pathway has been proved to regulate pyroptosis through the TXNIP/NLRP3 pathway in acute kidney injury, hepatocellular injury, preeclampsia, and other diseases." (PMID 36552271, 2022). "Furthermore, the absence of TXNIP may contribute to the improvement of acute kidney injury by promoting autophagy." (PMID 35314758, 2022).
cardiomyopathy (7 papers, 2022 to 2025). A disease of the heart muscle or myocardium proper. "In a DOX-induced mouse model of cardiomyopathy, cardiomyocyte senescence was linked to the upregulation of thioredoxin-interacting protein (TXNIP), which inhibited thioredoxin activity and disrupted intracellular antioxidant balance." (PMID 41584283, 2025).
chronic kidney disease (7 papers, 2023 to 2025). Impairment of the renal function secondary to chronic kidney damage persisting for three or more months. "This suggests that targeting TXNIP could be a potential strategy for preventing vascular calcification in patients with chronic kidney disease or other related conditions." (PMID 40610750, 2025).
Cognitive impairment (7 papers, 2018 to 2025). Abnormal cognition is characterized by deficits in thinking, reasoning, or remembering. "Resveratrol upregulates the expression of miR-146a-5p, thereby inhibiting TXNIP expression and alleviating the cognitive impairment associated with diabetic encephalopathy." (PMID 39058162, 2024). "Knockdown of hippocampal TXNIP significantly improves brain injury, cognitive impairment, and neuroinflammation, suggesting that TXNIP is a potential target for the treatment of these CNS disorders." (PMID 29386025, 2018). "In addition, knockdown of hippocampal TXNIP can remarkably improve cognitive impairment and neuroinflammation, which suggested that TXNIP is a potential treatment target for AD." (PMID 32309439, 2020). "Our findings further demonstrated that TXNIP overexpression contributed to neuronal injury by activating the ERS/NLRP3 inflammasome pathway, leading to cognitive impairments in DCD." (PMID 39629879, 2025).
colon carcinoma (7 papers, 2010 to 2024). "We utilized four machine learning algorithms to identify three key ferroptosis-related genes (TXNIP, SLC2A1, ATF3) that are closely associated with the development and prognosis of colon cancer from 52 differentially expressed genes." (PMID 38244591, 2024). "Whereas among the up-regulated genes, there are three pro-apoptosis genes including HRK, TXNIP and DDIT3, which may also helpful to explain how aspirin can induce cellular apoptosis in colon cancer." (PMID 28184026, 2017).
nonalcoholic steatohepatitis (7 papers, 2020 to 2025). "Moreover, a recent study revealed that TXNIP deletion alleviates hepatic steatosis and inflammatory responses in a mouse model of non-alcoholic steatohepatitis (NASH)." (PMID 39690856, 2025). "Studies have shown that TXNIP knockdown can upregulate the expression of tight junction protein ZO-1 and occluding in intestinal epithelial cells of mice with non-alcoholic steatohepatitis, reduce MPO activity and ROS levels, and reduce hepatitis-induced intestinal mucosal injury." (PMID 37530723, 2023).
renal fibrosis (7 papers, 2016 to 2025). A final common manifestation of a wide variety of chronic kidney diseases characterized by glomerulosclerosis and tubulointerstitial fibrosis. "Recent studies have shown that aging biomarkers are downregulated in TXNIP knockout mice and that these effects can lead to attenuation of renal fibrosis and renal impairment." (PMID 40160460, 2025). "Two independent studies demonstrated that TXNIP exhibits a pro-fibrotic property in renal fibrosis, but has been shown to exhibit an anti-fibrotic property in the liver." (PMID 38529321, 2024). "Overall, the upregulation of TXNIP was observed and implicated in pathological pathways in vivo and in vitro in the NS model, UUO-induced renal fibrosis model, aging-related renal fibrosis model, DN model, and human proteinuric kidney diseases." (PMID 37394581, 2023). "TXNIP deletion attenuates renal fibrosis and damage by regulating SMAD3 and p38/ERK MAPK phosphorylation in a unilateral ureteral obstruction (UUO) mouse model of renal interstitial fibrosis." (PMID 37394581, 2023). "TXNIP overexpression in tubular epithelial cells increases the expression levels of the cellular senescence markers p16INK4a and γH2AX and the profibrotic factors α-SMA, TGF-β1/SMAD3, and collagen I, which ultimately lead to aging-related renal fibrosis and a decline in kidney function." (PMID 37394581, 2023).
thyroid cancer (7 papers, 2014 to 2024). "The apparent loss of TXNIP expression during the progression from well-differentiated to poorly-differentiated and undifferentiated thyroid cancer is consistent with its role as a tumor suppressor in thyroid cells." (PMID 24645981, 2014). "It is reported that TXNIP is a tumor suppressor, which has been verified in various cancers, including breast, lung, and thyroid cancer." (PMID 36445321, 2022). "validated that higher-expression of TXNIP significantly suppressed the growth of T238 cells and reduced metastasis of thyroid carcinoma in a mouse model." (PMID 34277424, 2021). "Thioredoxin‐interacting protein (TXNIP) has been widely recognized as a tumor suppressor in various cancers, including liver, breast, and thyroid cancers." (PMID 32511893, 2020). "In thyroid cancer, for example, the total proportion of TXNIP-positive tumors is higher in papillary carcinomas (41.9%), which are associated with the most favorable prognosis amongst thyroid cancer subtypes." (PMID 33081035, 2020). "With the development of proteomics and genomics and the continuous progress of research on thyroid cancer, researchers have found that TXNIP is closely related to PTC." (PMID 33194655, 2020). "Our findings indicate that TXNIP functions as a tumor suppressor in thyroid cells, and its downregulation is likely important in the transition from differentiated to advanced thyroid cancer." (PMID 24645981, 2014). "Western blot analysis and immunohistochemistry (IHC) were used to assess thioredoxin interacting protein (TXNIP) expression in thyroid cancer cell lines and primary tumor specimens." (PMID 24645981, 2014). "TXNIP is downregulated during the progression from well-differentiated thyroid cancers to poorly differentiated and anaplastic thyroid cancers." (PMID 24645981, 2014). "Based on its differential expression in DTC and ATC, we predicted that TXNIP acts as a tumor suppressor in thyroid cells and that its downregulation plays an important role in the development of an aggressive thyroid cancer phenotype." (PMID 24645981, 2014). "Future studies of the mechanisms by which TXNIP is expressed and functions in thyroid cancer will improve our understanding of the progression to advanced thyroid cancer and help to develop more effective targeted therapies." (PMID 24645981, 2014). "In keeping with the known function of TXNIP as a glucose uptake inhibitor, we showed that the degree of glucose uptake was inversely correlated with TXNIP levels in the examined thyroid cancer cell lines." (PMID 24645981, 2014). "An orthotopic thyroid cancer mouse model was used to assess the effect of TXNIP overexpression in ATC cell lines in vivo." (PMID 24645981, 2014). "Disruption of TXNIP is important for the development of breast and thyroid cancers." (PMID 32511893, 2020). "Importantly, TXNIP overexpression in T238 cells results in attenuated tumor growth and decreased metastasis in an orthotopic thyroid cancer mouse model." (PMID 24645981, 2014). "Importantly, in an in vivo orthotopic murine thyroid cancer model, TXNIP overexpression attenuated tumor growth and drastically diminished pulmonary metastatic tumor burden." (PMID 24645981, 2014). "In conclusion, we report that TXNIP is a novel tumor suppressor in thyroid cancer." (PMID 24645981, 2014). "In this report, we identified TXNIP as a novel tumor suppressor in thyroid cancer." (PMID 24645981, 2014). "Therefore, loss of or absence of TXNIP expression appears to correlate with more aggressive thyroid cancer in cell lines and tumor tissue." (PMID 24645981, 2014). "Importantly, in a well-established orthotopic murine thyroid cancer model that mimics human thyroid cancer with regard to growth and metastasis, we show that TXNIP overexpression in the ATC T238 cell line resulted in significant attenuation of both tumor growth and pulmonary metastatic burden." (PMID 24645981, 2014).
thyroid cancer (continued). "This differential TXNIP expression between PTC and ATC is similar to the pattern observed with the thyroid cancer cell lines." (PMID 24645981, 2014). "In this current study, we show that TXNIP is highly expressed in DTC and low or undetectable in ATC and appears to be a novel tumor suppressor in thyroid cancer." (PMID 24645981, 2014). "The novel finding that TXNIP expression is low in ATC is consistent with the observed FDG uptake on PET/CT in patients with ATC, supporting a critical role for TXNIP as a metabolic regulator in thyroid cancer progression." (PMID 24645981, 2014). "The exact mechanisms by which TXNIP exerts its tumor suppressive functions in thyroid cancer cells are not yet clear." (PMID 24645981, 2014). "TXNIP has been shown to be a tumor suppressor in cancer, but its role in thyroid cells or in thyroid cancer has not been investigated." (PMID 24645981, 2014). "TXNIP is a known tumor suppressor whose role in thyroid cancer has never been reported." (PMID 24645981, 2014). "The novel finding that TXNIP expression is lost in the progression from well-differentiated PTC to undifferentiated, aggressive ATC is consistent with our hypothesis that TXNIP is a tumor suppressor in thyroid cancer." (PMID 24645981, 2014). "This TXNIP expression pattern is opposite to what we previously reported with PPARγ, which is highly expressed in ATC cell lines and absent in DTC cell lines and whose forced expression confers a more aggressive phenotype in thyroid cancer cells in vitro and in vivo." (PMID 24645981, 2014).